TSPO (translocator protein)
Diseases named in the same sentence as TSPO in open-access papers (continued):
Sharing a sentence is not in itself a finding about the gene and the disease.
glioblastoma (continued). "Both TSPO and NOX4 promoted angiogenesis in an ROS-dependent manner, suggesting that TSPO triggered ROS production in glioblastoma via NOX4." (PMID 36278207, 2022). "Here, we investigated TSPO PET imaging and autoradiography in the frequently used GL261 glioblastoma mouse model and aimed to generate insights into the temporal evolution of TSPO radioligand uptake in glioblastoma in a preclinical setting." (PMID 35453488, 2022). "As recently shown, longitudinal TSPO PET imaging in glioblastoma in vivo models is an efficient tool to monitor treatment response and delivers different information compared to established tracers." (PMID 35453488, 2022). "Here, e.g., longitudinal double tracer PET studies including both [18F]FET and [18F]GE-180 in glioblastoma mouse models would be helpful to gain further in vivo insights on the inflammatory contribution to the TSPO PET signal." (PMID 35453488, 2022). "One pilot study evaluating the TSPO PET tracer 11C-PBR28 in patients with primary glioblastoma multiforme or melanoma brain metastasis, treated with chemoradiation or immunotherapy, was completed recently; the results are to be determined (NCT02431572)." (PMID 35115369, 2022). "TSPO-targeting radioligands have mainly been tested in glioblastoma, due to the overexpression of TSPO in activated microglial cells next to its expression in TAMs." (PMID 35788730, 2022). "This is supported by a case series of three glioblastoma patients reporting that an increased or discordant TSPO signal compared to [18F]FET PET predicted areas of tumor progression." (PMID 35008218, 2021). "In U118MG human glioblastoma cells, TSPO knockdown attenuated the ROS generation of cobalt chloride (CoCl2)." (PMID 33066460, 2020). "Exposure of U118MG glioblastoma cells to CoCl2 resulted in increased apoptotic cell death, while TSPO knockdown prevented this cytotoxic effect of CoCl2." (PMID 32370132, 2020). "The TCGA glioblastoma dataset was analysed for the expression of TSPO and SLC7A5 (=LAT1), encoding for the molecular targets of TSPO- and FET-PET, and for AIF1, as we found a high TSPO level in microglia and macrophages." (PMID 31963507, 2020). "After implantation of syngeneic GL261 glioblastoma cells in both wild-type Tspo+/+ and Tspo−/− mice animals, selective TSPO radioligand [18 F]PBR111 microPET/MRI/CT imaging revealed highly expressed TSPO in the tumour mass." (PMID 32561881, 2020). "The OMM-localized 18 kDa translocator protein (TSPO) is demonstrated to inhibit mitochondrial Ca2+ uptake by promoting VDAC1 phosphorylation, while VDAC1 ablation in human glioblastoma U87 cells leads to reduced levels of TSPO." (PMID 33195204, 2020). "TSPO knockdown in U118MG glioblastoma cells, demonstrated the important role of TSPO in apoptosis induced by CoCl2, including processes such as: Δψm depolarization, cardiolipin peroxidation, and ROS generation." (PMID 32370132, 2020). "In our recent study, we demonstrated that down-regulation of VDAC1 in glioblastoma (GBM) also down-regulated TSPO expression." (PMID 31288390, 2019). "Our findings that down-regulation of VDAC1 in glioblastoma also down-regulated TSPO expression suggests that this should affect the tumor functions supported by TSPO such as metabolism, and cell proliferation." (PMID 31661894, 2019). "On the other hand, PK11195 was reported to be able to induce changes in expression of immediate early genes and transcription factors in U118MG glioblastoma cells which were studied for TSPO functions for years." (PMID 30532709, 2018). "Angiopoietin-2 (Ang-2), an angiogenic growth factor, was overexpressed in bevacizumab-treated glioblastomas, while translocator protein (TSPO) was upregulated in bevacizumab-treated glioblastomas and promoted apoptosis resistance." (PMID 28993773, 2017).
glioblastoma (continued). "The suggestion that TSPO can serve to catalytically metabolize PPIX to tetrapyrrole products other than hemin in human U118MG glioblastoma cells was recently corroborated for TSPO from Bacillus cereus, Xenopus, and mammals, in addition to humans." (PMID 27271616, 2016). "Studies in other human cells have shown that TSPO is a major participant in the modulation of gene expression in human glioblastoma cells." (PMID 27271616, 2016). "Generation of [18F]-AB5186 through 18F incorporation was achieved in good radiochemical yield and subsequent in vitro and ex vivo autoradiography revealed the ability of this compound to bind with specificity to TSPO in mouse glioblastoma xenografts." (PMID 29142713, 2015). "Back-translation into syngeneic glioblastoma mice pinpointed myeloid cells as the predominant source of contralateral TSPO-PET signal increases and identified a complex immune signature characterized by myeloid cell activation and immunosuppression in distant brain regions." (PMID 39150564, 2024). "Interestingly, the only two patients presenting with persistent generalized tonic-clonic seizures indicated highest contralateral TSPO-PET signals among the group of patients with glioblastoma suffering from epilepsy." (PMID 39150564, 2024). "Thus, for critical interpretation of our clinical findings, we performed back-translation into a murine SB28 glioblastoma mouse model and deciphered myeloid cells as the cellular source of increased contralateral TSPO-PET signals." (PMID 39150564, 2024). "In vivo imaging data were correlated with data obtained by autoradiography (ARG) and immunohistochemistry (IHC) to gain a detailed insight on the nature of cell populations that account for the positive TSPO PET signal of orthotopically implanted glioblastomas." (PMID 38255293, 2024). "In contrast, we observed higher TSPO expression in the contralateral hemisphere of SB28 glioblastoma mice compared to sham and healthy mice, suggesting that largely increased TSPO expression does not originate from major infiltration of tumor cells at the contralateral site." (PMID 39150564, 2024). "Furthermore, TSPO antibody-based therapy inhibited tumor growth, decreased vascular permeability and provided effective therapy against glioblastomas." (PMID 37407961, 2023). "We hypothesized that TSPO plays a critical role in NOX4-mediated extracellular ROS production in glioblastoma." (PMID 36278207, 2022). "TSPO–Nox4 signaling seems to be a promising molecular therapeutic target for glioblastoma." (PMID 36278207, 2022). "Therefore, we investigated the role of TSPO in subsequent NOX4-derived ROS generation in glioblastoma." (PMID 36278207, 2022). "We analyzed if targeting TSPO with XBD173 affects ROS production of glioblastoma in vivo." (PMID 36278207, 2022). "Thus, the increased background TSPO upregulation over time in the GL261 model would support the conception of glioblastoma being a disease of the entire brain." (PMID 35453488, 2022). "In this multimodal longitudinal [18F]GE-180 PET study we corroborate the translocator protein TSPO as an interesting target for in vivo imaging of glioblastoma, as confirmed by ex vivo autoradiography, in vitro autoradiography and TSPO staining in a preclinical setting." (PMID 35453488, 2022). "The results could serve as a basis for exploring therapeutic targets based on the dual inhibition of NOX4 and TSPO in glioblastoma." (PMID 36278207, 2022). "In addition, they also reported new quinazoline-urea based compounds with potent cytotoxic activities against TMZ-resistant glioblastoma multiforme (GBM) cells, which may be associated with plausible binding modes in translocator protein 18 kDa (TSPO)." (PMID 35071184, 2021). "Moreover, the positive allosteric modulatory effect of koumine on TSPO was further demonstrated in cell proliferation assays in T98G human glioblastoma cells." (PMID 34248642, 2021).
glioblastoma (continued). "Later studies in human glioblastoma cells suggested that TSPO may be involved in the degradation of excess levels of PPIX, by means of ROS generation." (PMID 27271616, 2016). "Furthermore, studies on other disease targets, such as the role of the translocator protein (TSPO) in glioblastoma and the potential role of GPR35 in diabetes and hypertension, provide valuable references for understanding the mechanism of action of PF4V1 in NMOSD." (PMID 40294019, 2025). "Considering scRadiotracing and immunofluorescence data together, our results show that higher TSPO-PET signals do not solely derive from higher myeloid cell density in the contralateral hemisphere of glioblastoma animals but are predominately caused by higher TSPO expression of single myeloid cells." (PMID 39150564, 2024). "The 18 kDa translocator protein (TSPO) is increasingly recognized as an interesting target for the imaging of glioblastoma (GBM)." (PMID 35453488, 2022). "The 18 kDa translocator protein (TSPO) is increasingly recognized as an interesting target for the study of glioblastoma (GBM), the most common and aggressive primary malignant brain tumor in adults with a five-year survival rate of only 7.2%." (PMID 35453488, 2022). "We aimed to validate the hypothesis that TSPO regulates angiogenesis via NOX4 in glioblastoma." (PMID 36278207, 2022). "Overall, our review contributes to a better understanding of the functional significance of TSPO in Glioblastoma and draws attention to TSPO as a potential modulator of treatment response and thus an important factor that may influence the clinical outcome of GBM." (PMID 33066460, 2020). "The syngeneic tumour (TSPO+/+) in null background (TSPO−/−) model is thus well suited to study the interaction of the tumour front with the peri-tumoral tissue, and the experimental evaluation of new therapeutic approaches targeting the invasive behaviour of glioblastoma." (PMID 32561881, 2020). "Sub-region analysis revealed elevated contralateral TSPO-PET signals (all P < 0.01) in all temporal areas as well as in frontal and parieto-occipital lobes for patients with glioblastoma and persistent epileptic seizures." (PMID 39150564, 2024). "In particular, we observed a topological correlation between TSPO-PET signals in tumor seed regions and corresponding contralateral regions in patients with glioblastoma." (PMID 39150564, 2024). "To further characterize remote neuroinflammaton, we performed immunofluorescence in the cortex of the contralateral hemisphere of glioblastoma and sham mice and we analyzed the occupancy of IBA1 and TSPO positive myeloid cells." (PMID 39150564, 2024). "To estimate the influence of TSPO-expressing tumor cells in brain regions remote to the primary tumor site, we performed qPCR and analyzed eGFP expression in SB28 glioblastoma mice at the tumor and contralateral hemisphere." (PMID 39150564, 2024). "This selection process resulted in 41 patients with glioblastoma, IDH wild-type WHO 4 and seven patients with astrocytoma, IDH mutant (IDHmut) WHO 2 for further TSPO-PET analysis." (PMID 39150564, 2024). "For histopathological evaluation of TSPO as a PET imaging marker, we utilized IDH-wildtype glioblastoma (GBM) samples (n = 26) of our multidisciplinary prospective cohort." (PMID 37697350, 2023). "Concerning the extended investigation of TSPO functionality in glioblastoma, preclinical PET imaging studies have assessed the spatiotemporal relationship between TSPO and other pro- or anti-inflammatory markers to delineate functionally distinct tumor areas." (PMID 35804911, 2022).
glioblastoma (continued). "This was the first study to demonstrate that TSPO was the upstream target of NOX4-derived mitochondrial ROS, necessary for NOX4-derived mitochondrial ROS-induced angiogenesis in glioblastoma." (PMID 36278207, 2022). "Other publications corroborated an interaction of TSPO with cell cycle-related genes, e.g., in the U118MG glioblastoma cell line." (PMID 33066460, 2020). "In vitro and ex vivo autoradiography studies in mouse models of human glioblastoma, showed specific binding of [18F]-AB5186 to TSPO in tumour tissue." (PMID 29142713, 2015). "Still, contralateral TSPO-PET signal increases, as detected in patients, were robustly observed in the murine SB28 glioblastoma mouse model that only showed appearance of eGFP-positive tumor cells in the ipsilateral hemisphere, which was furthermore validated via qPCR." (PMID 39150564, 2024). "In MA-10 Leydig cells it has been shown that PKCε regulates TSPO gene expression through MAPK (Raf-1-MEK1/2-ERK1/2)-mediated transcriptional activation and we know that these pathways besides others are commonly dysregulated in glioblastoma." (PMID 37697350, 2023). "Histologically and on mRNA level, tumor cells express high levels of TSPO, especially glioblastoma as opposed to low-grade glioma." (PMID 36329288, 2023). "This might especially facilitate regional ex vivo co-localization of TSPO expression in the frame of double tracer PET studies, which gain increasing importance also for the understanding of the glioblastoma metabolism and microenvironment." (PMID 35453488, 2022). "Additional characterization indicated that [18F]GE-180 PET uptake was associated with the histological WHO grade, with the highest uptake values observed in WHO grade IV glioblastomas while all TSPO-negative cases were WHO grade II gliomas." (PMID 35804911, 2022). "In this study, both TSPO and NOX4 promoted angiogenesis in glioblastoma." (PMID 36278207, 2022). "Additionally, we observed a far higher TSPO expression in IBA1 positive cells of the non-lesion hemisphere of glioblastoma mice compared to sham (5.7-fold, P = 0.0048)." (PMID 39150564, 2024). "In addition, targeting simultaneously the angiogenic factor angiopoietin-2 (Ang-2) and translocator protein (TSPO), both of which are overexpressed in bevacizumab-treated glioblastomas, with a bispecific Ab in bevacizumab-treated rats resulted in prolonged survival." (PMID 33530460, 2021). "Therefore, we investigated the expression of TSPO and LAT1 in patient glioblastoma (GBM) samples, as well as in various GBM mouse models representing patient GBMs of different genetic subtypes." (PMID 31963507, 2020). "As patients with IDHmut astrocytoma WHO 2 did not indicate any relevant contralateral TSPO-PET changes compared to controls, we focused on patients with glioblastoma for subsequent analyses." (PMID 39150564, 2024). "We performed translocator protein (TSPO)-PET in patients with newly diagnosed glioblastoma (n = 41), astrocytoma WHO grade 2 (n = 7), and healthy controls (n = 20) and compared TSPO-PET signals of the non-lesion (i.e., contralateral) hemisphere." (PMID 39150564, 2024). "This assumption is supported by previous studies in which TSPO was shown to regulate the expression of coding and noncoding genes in U118MG glioblastoma cells." (PMID 30704062, 2019). "However, regarding human glioma imaging using TSPO-specific radiotracers, one has to take into account that not all types of glioma show equally high levels of TSPO expression as glioblastoma and this element could be exploited for the differential diagnosis of different types of these tumors." (PMID 25853015, 2015).
glioblastoma (continued). "Although TSPO ligands are widely used in molecular imaging in all sorts of CNS pathologies, little is known about the role of TSPO expression and neuroinflammation in glioblastoma patients and PET imaging with TSPO radioligands is not yet standard for the imaging of brain tumor patients." (PMID 31963507, 2020).
Parkinson disease (39 papers, 2016 to 2025). A progressive degenerative disorder of the central nervous system characterized by loss of dopamine producing neurons in the substantia nigra and the presence of Lewy bodies in the substantia nigra and locus coeruleus. "Campanella’s group previously documented that TSPO overexpression is linked to the loss of mitophagy in a model of Parkinson’s disease." (PMID 40563439, 2025). "Since the overall mitochondrial mass was unvaried, we investigated the expression of the Translocator Protein (TSPO), a small mitochondrial protein whose overexpression was recently linked to the loss of mitophagy in a model of Parkinson’s disease." (PMID 36792609, 2023). "Some human diseases such as Parkinson’s and Alzheimer’s are associated both with TSPO and with VDAC, suggesting an interplay between these partners in disease states." (PMID 34191248, 2021). "Elevated TSPO expression has been linked to neurodegenerative disorders, such as Parkinson’s disease (PD), as well as heart failure." (PMID 33383772, 2020). "Many studies have indeed demonstrated TSPO upregulation in patients affected by AD and in animal models of AD, but there is further evidence of a TSPO increase also in patients affected by Parkinson’s Disease." (PMID 39064171, 2024). "The resulting method was applied to a mouse model of Parkinson’s disease subjected to a test–retest study (n = 6) with the TSPO-specific radioligand [18F]VC701." (PMID 36138085, 2022). "TSPO is up-regulated in various neuropathological conditions, including AD, Parkinson’s disease (PD) and multiple sclerosis (MS)." (PMID 31288390, 2019). "Furthermore, there is well-documented evidence of putamen integrity decline in Parkinson’s disease (PD), along with increased TSPO levels, and recent findings from the UK biobank linking long sleep duration to an increased risk of PD." (PMID 41239401, 2025). "Furthermore, clinical imaging studies also indicate that TSPO significantly increases in neurodegenerative and neurological diseases such as Alzheimer’s disease (AD) and Parkinson’s disease (PD)." (PMID 32695005, 2020). "In addition, TSPO PET of patients with Parkinson’s disease with disease duration of less than 2 years showed inflammation in the midbrain, including SNc." (PMID 33716638, 2020). "Elevated putaminal uptake of TSPO tracer in frontotemporal dementia patients is consistent with the neuropathological (involvement of the basal ganglia) and clinical features (parkinsonism) of FTLD." (PMID 28387722, 2017). "However upon brain injury, augmented expression of TSPO is observed in activated glial cells and serves as a biomarker for disease activity in Alzheimer’s and Parkinson’s disease." (PMID 27315802, 2016). "Some initial studies reported high brain TSPO PET signal compared to controls in patients with AD, Parkinson’s disease (PD) and amyotrophic lateral sclerosis (ALS) and those at risk of Huntington’s disease (HD)." (PMID 38139248, 2023). "TSPO agent utility, however, extends beyond MS because similar pathophysiologic changes are also seen in ALS, Psychiatric disorders, Alzheimer’s, Parkinson’s, and Huntington’s disease, as well as colitis." (PMID 33925560, 2021). "The difference between activated state and density of cells may explain some of the discrepancies found between histopathological studies and TSPO-PET, for example in Parkinson's disease." (PMID 41257741, 2025). "Chronic α-synuclein model leads to an increase in TSPO without altering P2X7R expression, suggesting that increased P2X7R binding with TSPO is associated with neuroinflammation in acute but not chronic rodent models of Parkinson’s disease." (PMID 38247852, 2024). "In contrast to studies referenced above Koshimori and colleagues recently published data that did not clearly show an increase of TSPO expression in Parkinson’s disease patients as compared to healthy controls, using the second generation TSPO tracer [18F]-FEPPA." (PMID 27340650, 2016).